PPARG (peroxisome proliferator activated receptor gamma)
Diseases named in the same sentence as PPARG in open-access papers (continued):
Sharing a sentence is not in itself a finding about the gene and the disease.
cancer (continued). "The administration of curcumin in cancer treatment would thus appear to be an interesting therapeutic strategy, which acts through their role in regulating WNT/β-catenin pathway and PPARγ activity levels." (PMID 31331376, 2019). "This review focuses on the interest of use curcumin in cancer therapy by acting through the opposed interaction between the canonical WNT/β-catenin pathway and PPARγ to repress chronic inflammation and oxidative stress, and to control circadian rhythms." (PMID 31331376, 2019). "Though many researchers have studied the expression and clinical implications of PPARγ and PGC-1α in cancer, there are still many controversies about the role of PPARγ and PGC-1α in cancer." (PMID 29599799, 2018). "PPARγ and PGC-1α are emerging proteins involved in tumorigenesis and attractive topics to study for further understanding of cancer biology." (PMID 29599799, 2018). "Since one hurdle in treating cancer is its heterogeneity, our results provide a promising strategy for ATC treatment by targeting two independent metabolic pathways (HMGCR and PPARγ)." (PMID 29932104, 2018). "In cancers, apart from certain exceptions, the canonical WNT/β-catenin signaling is generally upregulated while PPARγ is downregulated." (PMID 29706964, 2018). "The PPARγ transcript was also significantly (P < .05) increased in A-549, MCF-7 and U87-MG cancer cells." (PMID 30460096, 2018). "Thus, COX-2 and PPARγ may concertedly inhibit cancer development." (PMID 30424016, 2018). "This review examines and summarizes some recent data on the role and action mechanisms of PPARγ and PGC-1α in cancer, respectively, particularly the recent progress in understanding the role of PPARγ in several cancers since our review was published in 2012." (PMID 29599799, 2018). "These authors demonstrated inhibition of cancer cell proliferation and function as NR ligands with DIM-Ph-CF3 being an NR4A1 and PPARγ agonist, and DIM-Ph-4-OMe a selective NR4A1 agonist." (PMID 29861853, 2018). "In the present study, even though the glucose uptake, and the expression of GLUT4 and GRβ transcripts were highly elevated in cancer cells, the expression of PPARγ transcription factor was also extremely increased in A-549 and MCF-7 cancer cells." (PMID 30460096, 2018). "The genes that were shared by three different cancers (i.e., FGFR3, EPAS1, SRC, and FOXD3) are shown in coral, and the genes that were shared by two types of cancers (i.e., PPARG, FOXO1, CDK4, NKX3-1, PIK3R1, PRKCB and EDNRB) are shown in light pink." (PMID 28178311, 2017). "The frequencies of PPARG c.1347 CC, CT and TT genotypes were 57.01%, 38.00% and 4.99% in 521 NSCLC patients and 61.32%, 34.50%, and 4.18% in 1,030 non-cancer controls, respectively." (PMID 29254243, 2017). "Several studies have shown that PPARγ/TZDs decrease IGF-1 levels and, thus, reduce cancer growth in carcinomas such as the pancreas, colon, liver, and prostate." (PMID 28348577, 2017). "Known activators of the Peroxisome Proliferator-Activated Receptor γ (PPARγ), thiazolidinediones (TZD) induce apoptosis in a variety of cancer cells through dependent and/or independent mechanisms of the receptor." (PMID 29296202, 2017). "In most cancers, the WNT/beta-catenin pathway is upregulated while peroxisome proliferator-activated receptor gamma (PPAR gamma) is downregulated." (PMID 28405929, 2017). "Experimentally, celecoxib suppressed cancer stemness and progression of HCC via activation of PPARγ and up-regulation of PTEN." (PMID 29098441, 2017). "TUG1 regulated the cancer genes ACVR1B and BCL2 in KIRC, while it competitively regulated PPARG in BLCA." (PMID 27580177, 2016). "A large body of literature on PPARγ and cancer was produced using TZD, which eventually were proved to have several anticancer pleiotropic effects also independently of PPARγ." (PMID 28115925, 2016). "However, whether and how PPARγ in macrophages modulates cancer progression is unknown." (PMID 27692066, 2016).
cancer (continued). "Peroxisome proliferator-activated receptor gamma (PPARG), another nuclear receptor, also has multiple functions mostly in metabolism, cancer development, cardiovascular diseases, bone diseases, etc." (PMID 25859557, 2015). "This overlap includes numerous PPARG target genes, including ANGPTL4 and AQP7, which were two of the six most highly induced genes in the human PPFP carcinomas." (PMID 26595524, 2015). "This study suggests that celecoxib suppresses cancer stemness and progression of HCC via activation of PPARγ/PTEN signaling." (PMID 24721996, 2014). "Among those genes are IFNGR2, PITX2, RFWD2, PPARγ, LOXL2, Rab6 and SPARC, all involved in cancer-related pathways." (PMID 24875049, 2014). "Furthermore, the role of PPARγ activation in cancer in general remains unclear." (PMID 23516550, 2013). "Furthermore, the role of PPARγ activation in cancer remains unclear." (PMID 23476786, 2013). "In this paper, our data were validated by the observation that cotreatment of PPARγ agonists and the AKT inhibitor triciribine strongly sensitized HCC cells to apoptosis and inhibited their cancer stem cell-like phenotype." (PMID 24023668, 2013). "Recent studies have provided evidence that the endogenously produced PPARγ antagonist, 2,3-cyclic phosphatidic acid (cPA), which is similar in structure to lysophosphatidic acid (LPA), inhibits cancer cell invasion and metastasis in vitro and in vivo." (PMID 22693486, 2012). "If PPARγ is involved in EMT, it is possible that PPAR has a role in the mechanism of metastasis of the cancer stem cells." (PMID 23316217, 2012). "Studies of primary thyroid tissue using immunohistochemical analyses generally show low levels of PPARγ in normal thyroid tissue and DTC, suggesting a limited role for this receptor in normal thyroid biology and differentiated cancer function." (PMID 22194735, 2011). "In the intestinal epithelial cells, PPARγ was shown to induce EMT, a process that is known to mediate cancer cell migration, invasion as well as acquisition of stem cell properties." (PMID 21144036, 2010). "In that the PPARγ agonist CDDO-Me inactivates Src and Stat3 in cancer cells, further investigation of the efficacy of various PPARγ ligands as anticancer agents is certainly warranted." (PMID 20204067, 2010). "In the current review, we discuss the molecular mechanisms and physiological implications of the crosstalk of PPARγ with MEK-ERK signaling and its potential as a novel drug target for cancer therapy in patients." (PMID 18596912, 2008). "Peroxisome proliferator-activated receptor-gamma (PPARγ), one of three ligand-activated transcription factors named PPAR, has been identified as a molecular target for cancer chemopreventive agents." (PMID 18779870, 2008). "In recent years, there has been a growing accumulation of data implicating theimportance of both PPARγ and PTEN in cancer prevention, development,and treatment." (PMID 19096712, 2008). "Many of the transcription factors with indirect effects, including PPARG, E2F1, STAT5A, and MYC, have been suggested as targets for cancer therapy." (PMID 18358079, 2008). "PPARγ expression, as well as SSAT and ODC mRNA levels were significantly higher in cancer as compared to normal mucosa." (PMID 16854216, 2006). "The present study has demonstrated for the first time substantial fall in gene transcription of the key adipogenic factors, C/EBPβ, C/EBPα, PPARγ and SREBP-1c, in white fat of cancer cachectic mice." (PMID 17047651, 2006). "In addition to promotion of cell differentiation, the PPARγ agonists-induced growth inhibition may involve various mechanisms such as induction of cell cycle arrest, inhibition of DNA synthesis, and increase of cancer cell necrosis and apoptosis." (PMID 15467764, 2004). "Levels of COX-2 and PPARγ proteins were determined by EIA in four benign tumours, three borderline tumours and 12 carcinomas." (PMID 15266333, 2004).
cancer (continued). "The possible apoptotic pathways for anti-cancer effects of curcumin on cell signal transduction include PI3K, Akt, mTOR, ERK5, AP-1, TGF-β, Wnt, β-catenin, Shh, PAK1, Rac1, STAT3, PPARγ, EBPα, NLRP3 inflammasome, p38MAPK, Nrf2, Notch-1, AMPK, TLR-4, and MyD-88." (PMID 41149437, 2025). "This suggests that the combination of short-course treatment with PPARγ agonists and NECTIN4-targeting anti-cancer therapy may be safe and feasible in the clinical setting, and warrants further investigation." (PMID 40931013, 2025). "Since PPARγligands primarily inhibit cancer cell growth, we cotreated Rh30 andA549 cells treated with PFOS alone and in combination with the PPARγinhibitors T007 and GW9662 expecting that by blocking PPARγ,PFOS-induced growth would be enhanced." (PMID 40066943, 2025). "Intriguingly, TGFβ impedes adipogenesis induction in cancer cells by inhibiting PPARγ expression but not C/EBPα, thus suggesting a direct effect of TGFβ-induced MEK-ERK activation on PPARγ regulation." (PMID 39273076, 2024). "Peroxisome proliferator-activated receptor gamma (PPARG), a ligand-activated nuclear transcription factor, plays a pivotal role in regulating gene expression and is known for its anti-inflammatory and anti-proliferative effects in various cancers." (PMID 39201328, 2024). "The regulation of gene expression by NR is crucial for metabolism, cancer, neurological diseases, development, and immune responses, with key target genes, such as those for the GR, AR, PGR, ER, and PPARγ, governing specific pharmacological effects in particular tissues." (PMID 39065726, 2024). "PPARG activation suppresses cancer cell spread by inhibiting epithelial–mesenchymal transition (EMT) and blocking TGFB-induced EMT, ultimately reducing the metastatic potential of cancer cells." (PMID 39201328, 2024). "Previous studies suggested that activation of PPARγ is related to the inhibition of proliferation of cancer cells rather than induction of cell death." (PMID 36834531, 2023). "As such, PPARγ drives pro-tumoral functions of group 2 innate lymphoid cells (ILC2) which protect against infection by helminths via the release of IL33, an alarmin overexpressed in cancers." (PMID 37686465, 2023). "DFI data analysis revealed a strong association between high PPARG expression and PAAD, unlike in other human cancers where it was not statistically significant." (PMID 38044948, 2023). "First, we chose human cancer cell lines that did not demonstrate PPARγ expression or a response to rosiglitazone treatment in order to concentrate on stromal effects in vivo." (PMID 37816052, 2023). "A heterodimer formed by activated peroxisome proliferator-activated receptor gamma (PPARγ) and RXR increases the rate of apoptosis in a variety of cancer cells by binding to PPAR response elements and recruiting co-activators and various other nuclear regulatory proteins." (PMID 35276890, 2022). "Also, 9-cis-retinoic acid suppressed cancer cells in CRC by increasing apoptosis and inhibiting COX-2 through the activation of PPARγ, while retinal suppressed CRC by inducing HOXA5 and repressing stem cell markers prominin 1 and ALDH1." (PMID 35178443, 2022). "In TLR4-transfected cancer coli-2 (Caco-2) cells, the TLR4 signaling pathway upregulates PPARγ expression as well as the expression of a PPARγ-dependent reporter in an inhibitor of nuclear factor kappa-light-chain-enhancer of activated B cells (Iκβ)-dependent manner." (PMID 35222098, 2022). "When FZD9 binds to Wnt7a in the lung epithelium and initiates anti-cancer signaling through PPARγ, it does not activate canonical β-catenin signaling." (PMID 35924166, 2022). "Both human NSCLC and SCLC cells exhibited PPARγ mRNA and protein, and reported that ligands such as ciglitazone and 15-deoxy-δ-12,14-prostaglandin J2 (15d-PGJ2) suppressed the growth of cancer cells at particular doses or times, with ciglitazone being less effective than 15d-PGJ2." (PMID 35631448, 2022).
cancer (continued). "In our setting of PPARγ targeting in ILC2s, the observed anti-tumoral phenotype obtained by the in vivo conditional and inducible genetic deletion of PPARγ in ILCs suggests that ILC-specific and temporal targeting of PPARγ might beneficial in cancer." (PMID 33953160, 2021). "Although multiple pro-tumorigenic mechanisms of PPARγ have been found, to date, there is no consensus if these PPARγ-mediated pathways are ubiquitous in different cancer cell types." (PMID 33946986, 2021). "Even though the traditional PPARγ agonists have many unwanted side effects, there are no substitute values for treatment in cancer or IRI warrant identification." (PMID 33995008, 2021). "Furthermore, in the environment of a human IL-33-enriched cancer type, such as CRC, ILC2s show PPARγ-dependent pro-tumoral functions." (PMID 33953160, 2021). "Importantly, we reported the activation of HSYA on PPARγ/PTEN/Akt signaling and PPARγ down-regulation reversed the anti-cancer effect of HSYA on CRC." (PMID 34889713, 2021). "Although there are no data directly linking PPARG with AML, it is worth mentioning that the protein is implicated in the TGF-beta and mTOR signaling pathways, both associated with cancer development." (PMID 34502231, 2021). "Besides the transcriptional effects on GPRs involved in cell metabolism, PPARγ was shown to downregulate the chemokine receptor CXCR4, which is highly expressed in cancer cell metastasis." (PMID 33799988, 2021). "The negatively correlated genes were enriched in “calcium signaling pathway,” “PPAR signaling pathway,” and “proteoglycans in cancer”, and ACACB, PPARG, CAV1 may be the core of these genes." (PMID 34257557, 2021). "In inflammation and cancer, TNF‐α inhibits the activity of PPARγ via IκBα‐mediated signalling." (PMID 34302428, 2021). "However, the connection between exosomes and PPARγ still represents an unexplored research avenue, and thus investigating the future the role of this receptor as an exosomal cargo or as an exosome specific target may shed new light in cancer prevention and treatment." (PMID 33352766, 2020). "Thus, PPARγ-agonist facilitates nuclear accumulation of MTMR7 in vitro and ex vivo in patient-derived cancer stem cells." (PMID 32522977, 2020). "Based on the TCGA database, Pearson analysis showed a negative correlation of PTEN and PPARγ expression in BCa 13, which greatly different compared with other cancers." (PMID 32328200, 2020). "Further investigations are required to figure out the potentials of PPARs and their coactivators as drug targets for cancer, which makes our study even more important in the contribution to the expression signature analysis of PPARA, PPARD, PPARG, PPARGC1A, and PPARGC1B." (PMID 33029111, 2020). "Thus, FaDOH could have multiple effects on cancer cells from upregulation of lipid uptake, to increased ER stress, both which could lead to the increased LD formation we observe, but FaDOH could also have anticancer effect by downregulation of β-catenin through PPARγ." (PMID 32982759, 2020). "In addition to PPARγ, the other PPAR subtypes PPARα and PPARδ have been also reported to play important roles in regulating cancer cell growth." (PMID 33266062, 2020). "Control of MMP-9 secretion is a known anti-inflammatory effect of pioglitazone and other PPARγ ligands; they can modulate septin-2 in cancer cells preventing MMP-9 actions, and during the course of intestinal inflammations, down-modulation of PPARγ can make MMP-9 more stable." (PMID 33519451, 2020). "In addition, AM360 abrogated BCP effects on both PPARγ and JNK expression, restoring the protein levels of untreated cancer cells." (PMID 32340197, 2020). "Another agonist of PPARG, curcumin, was able to eliminate oxidative stress and chronic inflammation via downregulating the WNT/β-catenin pathway, which is observed to have aberrant activation in many cancers." (PMID 33029111, 2020). "PPARγ is a member of the PPAR family and is expressed in a variety of cancers." (PMID 32328200, 2020).
cancer (continued). "Moreover, the previous studies have considered that PPARγ activation with thiazolidinedione class chemicals, such as PGZ, can induce the cellular apoptosis pathway in the cancer cells as a kind of chemotherapeutic agent, as shown in the present study." (PMID 33456717, 2020). "The studies signify the importance of PPARγ and PTEN’s interaction in cancer prevention." (PMID 32708484, 2020). "With the exception of three clusters of NRs representing NR classes I (cluster I: RORC, VDR, PPARA, NR1D1, THRA, RORA, NR1H3; cluster II: RARB, PPARG, THRB) and III (cluster III: ESR1, PGR, AR, ESRRG), NR class was not a good determinate of NR expression patterns in the different cancer types." (PMID 32024906, 2020). "In addition, GSEA results showed that these PPARG-driven chemosensitivity promoters were mainly enriched within the cell proliferation-related pathways, indicating that PPARG may influence the chemosensitivity through the regulation of carcinoma-related cell proliferation pathways." (PMID 32373170, 2020). "In cancers, the WNT/β-catenin pathway is generally activated whereas PPARγ is decreased." (PMID 31311204, 2019). "Moreover the interplay with other pathways, such as PPARγ and WNT/β-catenin, involved in metabolic enzymes changes in other cancers should be further investigated." (PMID 31544066, 2019). "Outside BRAFV600E, the likelihood of cancer for those variants documented as positive in at least 10 nodules in the included studies (BRAFK601E, HRASq61R, NRASq61R, and PAX8/PPARG fusion) ranged from 37% to 55%." (PMID 31469053, 2019). "In cancers, the WNT/β-catenin pathway is upregulated whereas PPARγ is downregulated." (PMID 31331376, 2019). "Together, these results suggest that PPARG can sensitize otherwise resistant NSCLC to radiation and hence can be considered as a potential target to improve the radiotherapeutic procedure for these cancer types." (PMID 31263479, 2019). "NSAIDS act as peroxisome proliferator-activated receptor gamma (PPARγ) agonists and could thus downregulate the aberrant WNT/β-catenin pathway in cancers." (PMID 31311204, 2019). "The potential of PPARG in combination with radiation, against cancer cell has not been investigated in detail." (PMID 31263479, 2019). "Taken together, these studies suggest that PPARγ agonists could prevent CINP and improve the efficacy of cancer chemotherapy." (PMID 31555078, 2019). "Moreover, in cancers, the disruption of circadian clock leads to the increase of the WNT/β-catenin pathway and to decrease of PPARγ expression." (PMID 31331376, 2019). "In addition, 5-KETE had a concentration-dependent effect on proliferation in cancer cell lines; high concentrations of 5-KETE inhibited proliferation via the peroxisome proliferator activated receptor gamma pathway." (PMID 31636603, 2019). "In cancers, the canonical WNT/β-catenin pathway is overactivated while PPARγ is decreased." (PMID 31311204, 2019). "In mainly cancers, the canonical WNT/β-catenin pathway is increased while PPARγ is downregulated." (PMID 31331376, 2019). "In the case of carcinomas, the level of TLR-2 was increased while PPARγ was decreased." (PMID 31011554, 2019). "In most cancers, the canonical WNT/β-catenin pathway is increased while PPARγ is downregulated." (PMID 29706964, 2018). "In this study, the expression of GLUT4 transcript and ratio 0f glucose uptake were highly increased in U87-MG cancer cells after being exposed to DEX, while expression of PPARγ and GRβ transcripts was detected at very low level when compared to other cancer cell lines." (PMID 30460096, 2018). "Cancers, such as gliomas and colon cancer, present an upregulation of the canonical WNT/β-catenin pathway associated with a decrease of PPARγ expression." (PMID 29659554, 2018). "PGC-1α is also now known to play important roles in cancer, independent of the role of PPARγ in cancer." (PMID 29599799, 2018).